IL10 (interleukin 10)
Diseases named in the same sentence as IL10 in open-access papers (continued):
Sharing a sentence is not in itself a finding about the gene and the disease.
ovarian carcinoma (continued). "Treating murine and human myeloid DCs with exogenous IL-10 increases PD-1 expression and amplifies production of IL-10, leading to suppressed T and B cell responses and acquisition of resistance to anti-PD-1 therapy by ovarian cancer cells." (PMID 35310881, 2020). "TAMs have also been implicated in their ability to polarize Treg cells from CD4+ help T cells through their secreted TGFβ and IL-10 in epithelial ovarian cancer patients, indicating the involvement of TAMs in accelerating cancer progression through weakening anti-tumor immunity." (PMID 32283687, 2020). "In addition, it inhibits the cancer-promoting factors, including VEGF, MMP9, MMP2, and IL-10, in macrophages stimulated by ovarian cancer cells." (PMID 30871059, 2019). "Mechanistically, LL-37 stimulates MSCs to secrete larger amounts of inflammatory and pro-angiogenic factors, such as IL-1 receptor antagonist, IL-6, IL-10, CCL5, VEGF, and MMP-2, and this phenomenon is closely associated with the promotion of ovarian cancer progression and metastasis." (PMID 30568223, 2019). "Furthermore, they observed that concentration of IL-10 in ovarian cancer cell lysate was markedly higher than its serum level, which points to tumor microenvironment as a principal source of this cytokine." (PMID 28376925, 2017). "Furthermore, several studies have demonstrated highly significant associations between the ascites levels of various cytokines and the relapse-free survival (RFS) or overall survival (OS) of ovarian cancer patients, for example, TGFβ, IL-6, IL-10, and LIF." (PMID 28275576, 2017). "Also median concentrations of IL-10 in peritoneal fluid turned out to be the highest in ovarian cancer patients, followed by women with endometrioma and subjects with benign serous cysts." (PMID 28376925, 2017). "IL10 suppresses proinflammatory cytokine secretion, antigen presentation and CD4+ T cell activation and CCL22 is associated with regulatory T-cell migration in ovarian cancer." (PMID 28266500, 2017). "Upregulated PD-L1 expression in chemoresistant ovarian cancer cells might affect tumour-reactive T-cell function and PD-L1-induced IL-10 expression." (PMID 27147225, 2016). "Higher levels of CA125 and IL-10 in the serum of patients might indicate that the combination of these biomarkers could be used for distinguishing patients with ovarian cancer from those with benign cysts." (PMID 25999622, 2015). "The aim of the current study was to determine whether there are differences in immunohistochemical tissue staining of cytokine tumor necrosis factor-α (TNF-α) and interleukin-10 (IL-10) between benign tumors and malignant primary ovarian cancer." (PMID 25624918, 2015). "In addition, IL-10 and CA-125 contents were measured in the serum of those patients to evaluate if the combination of these molecules would be able to differentiate ovarian cancer from ovarian cyst." (PMID 25999622, 2015). "Similarly, IL-10, produced by TAMs, is increased in ovarian cancer and correlated with higher tumor grade and poor patient outcome." (PMID 24936477, 2014). "The cytokines, including IL-4 (p = 0.017) and TNF-α (p = 0.046), significantly decreased while others such as TGF-β (p = 0.013), IL-6 (p = 0.016), and IL-10 (p = 0.018) were elevated in ascites of ovarian cancer patients, when the disease progressed to advanced stages." (PMID 23082146, 2012). "Furthermore, elevated level of serum cytokines IL-2, IL-5, IL-6, IL-10, and TNF-α in ovarian cancer patients, might be associated with ovarian cancer progression." (PMID 37322531, 2023). "Furthermore, the malignant cases also showed significantly high IL-10 levels in the serum and ascitic fluid, suggesting that malignant cells can synthesize interleukin, which likely assists in the promotion and development of ovarian carcinoma." (PMID 25624918, 2015).
ovarian carcinoma (continued). "In addition, the malignant tumors had significantly higher serum and ascitic fluid IL-10 levels, suggesting that the malignant cells were able to synthesize this IL, and that it may contribute to the promotion and development of ovarian carcinoma." (PMID 25624918, 2015). "Studies have demonstrated that IL-10 may be involved in the progression of ovarian cancer." (PMID 25624918, 2015). "Moreover, IL-10 producing monocytes and select populations of the myeloid lineage, which inhibit T cell proliferation, have been isolated from the ascites of patients with ovarian carcinomas." (PMID 23533029, 2013). "In addition to above, malignant ascites contains significant numbers of activated CD163+ M2 type of macrophages the presence of which correlates with enhanced levels of IL-6 and IL-10 and inversely correlates with relapse-free survival period in ovarian cancer patients." (PMID 24093089, 2013). "For example, the presence of IL-10 and TGF-β in the ascites of ovarian cancer patients is a clear example of environmental inhibition of post-vaccination response." (PMID 40362280, 2025). "M2 macrophages, characterized by high levels of anti-inflammatory markers such as IL-10 and reduced pro-inflammatory factors like TNF-α, contribute to the immune suppression, tumor progression, and metastasis commonly seen in ovarian cancer." (PMID 40330466, 2025). "Following the bioinformatics analysis, the study explored the expression levels of CCL2, IL10, IL6, and TGFβ1 in normal ovarian epithelial cells (HOSE) and ovarian cancer cells (SKOV3)." (PMID 39981173, 2025). "Suppresses ovarian cancer cell proliferation and macrophage-induced protumor effects by inhibiting STAT3; reduces IL-10 and other M2 markers in macrophages; enhances sensitivity to chemotherapy drugs (e.g., CDDP, PTX) in cancer cells." (PMID 40330466, 2025). "In ovarian cancer, CSCs activate macrophages, driving them to adopt an immunosuppressive M2-like phenotype, characterized by increased CD206 expression and IL-10 secretion." (PMID 40330466, 2025). "To further prove the relationship between ALKBH5 and M2 macrophage markers in TME of ovarian cancer, we found that ALKBH5 positively correlated with M2 macrophage markers IL-10 and CD163 through Pearson analysis in ovarian cancer related dataset GSE158739." (PMID 38637813, 2024). "Some evidence has indicated that IL-10 has suppressive effects on angiogenesis, tumour growth, and peritoneal dissemination of VEGF-producing ovarian cancer cells." (PMID 38459564, 2024). "The co-cultured ovarian cancer cells show increased expression of PD-L1, VEGF, STAT3, IL-10, IL-6, B-cell lymphoma 2 (BCL2), and MDR1." (PMID 36757936, 2023). "Cytokines (IL-6, TNF-α, IL-10, TGF-β) and chemokines (CCL2, CCL4, CXCL10) involved in the ovarian cancer microenvironment have also been shown to contribute to the development of carcinogenesis." (PMID 36765633, 2023). "An increase in IL-3 and IL-10 expressions, insulin-like growth factor binding proteins (IGFBP) IGFBP-1, IGFBP-2 and IGFBP-3 levels were detected in both ovarian cancer cell lines with leptin administration." (PMID 37155466, 2023). "We determined that TAMs had increased expression of IL-10, IL-6, CD206, and ARG1, whereas ovarian cancer cells had increased expression of IL-10, IL-6, VEGF, STAT3, and PD-L1." (PMID 36757936, 2023). "Significantly reduced expression of NKG2D, high level of MICA as well as IL-6, IL10 and TNF-α indicates immune suppression of ovarian cancer patients.." (PMID 37322531, 2023). "Ovarian cancer stem cells and macrophages grown together in spheroids result in increased CD206, CD163, and IL-10 expression, as well as WNT signaling pathway activity, compared with ovarian cancer cells grown in isolation." (PMID 37545408, 2023). "In general, higher serum levels of Il-10, Il-6, and TGF-β are reported in women with advanced ovarian cancer compared to controls." (PMID 35565348, 2022).
ovarian carcinoma (continued). "Platinum-agents have demonstrated increased IL-6 and PGE2 production in ovarian cancer cell lines, with subsequent activation of STAT3 pathway and induction of M2 polarization with upregulation of IL-10." (PMID 35565348, 2022). "High IL-10 and low IFN-γ concentrations in ascites from ovarian cancer patients were correlated with poor prognosis and skewed immune cell differentiation towards immune-suppressive and tumor-promoting phenotypes." (PMID 34956861, 2021). "Several adverse clinical markers are highly expressed by ovarian cancer TAMs, including CD163, Procollagen C-endopeptidase enhancer 2 (PCOLCE2), IL-6 and IL-10." (PMID 32774171, 2020). "CD163 and MRC1 mRNA expression also correlated with the ascites levels of IL-10, which is prognostic of a short RFS of ovarian cancer." (PMID 29141914, 2018). "The ovarian cancer TME is particularly immunosuppressive with high levels of immunoregulatory mediators such as PGE2, IL-10, VEGF and others, all correlating with tumor progression and poor prognosis." (PMID 30477198, 2018). "Median concentrations of IL-10 and TNF-alpha in peritoneal fluid turned out to be the highest in ovarian cancer patients, followed by women with endometrioma and subjects with benign serous cysts." (PMID 28376925, 2017). "In a mouse model of ovarian cancer, CX3CR1-expressing myeloid cells promoted immunosuppression through inhibition of T-cell activity by IL-10, suggesting that CD11b+CX3CR1+ cells function as MDSCs." (PMID 29190915, 2017). "Higher levels of CA125 and IL-10 in the serum of patients with ovarian cancer compared to patients with ovarian cysts might indicate that the combination of these biomarkers could be used for distinguishing patients with ovarian cancer from those with benign cysts." (PMID 25999622, 2015). "To study the effect of Treg cells on the immunity of ovarian cancer cells, we quantified the secretion of the cytokines TGF-β, IFN-γ, IL-2, IL-10 and perforin in the different co-culture groups." (PMID 25376937, 2015). "Deleting IKKβ in myeloid cells diminished expression of IL-10, IL-12p70, TNF-α cytokines and reduced size of tumors formed by ovarian cancer ID8 cells." (PMID 26427514, 2015). "In order to investigate the effect of Treg cells on the immunity of ovarian cancer cells, we measured the concentrations of TGF-β, IFN-γ, IL-2, IL-10 and perforin in the cell supernatants using ELISA." (PMID 25376937, 2015). "In OVC Module 8, STAT5B-STAT3 gene pair is activated in ovarian cancer, interacts with each other, and is involved in many pathways including Jak-STAT signaling, RAS signaling, Chemokine signaling, EGF, IL10, PDGF, and TPO pathways." (PMID 23940583, 2013). "IL-4, IL-10 and TGF-β are also central to macrophage-mediated immunosuppression in ovarian cancer." (PMID 40330466, 2025). "Pro-tumorigenic cytokines such as interleukin-6 (IL-6) and interleukin-10 (IL-10) enhance MDSC recruitment and function through activation of the STAT3 signaling pathway, while VEGF and adenosine secreted by ovarian cancer cells further facilitate their accumulation and immune-suppressive effects." (PMID 41301911, 2025). "Despite the pro-tumorigenic role of IL10 in PDA, it may play a role in the reduction of tumor vascularity in ovarian cancer." (PMID 38824552, 2024). "In syngeneic mouse models of ovarian cancer (OvCa), tumor expression of Egfl6 increased the intratumoral accumulation of polymorphonuclear (PMN) MDSCs and TAMs and their expression of immunosuppressive factors, including CXCL2, IL-10, and PD-L1." (PMID 39312740, 2024). "Some studies had found that ETS1 exosomes secreted by ovarian cancer cells induce the polarization of M2 macrophages, which overexpress CD163, IL-10, CCL2, CXCL5 and other immunosuppressive factors, and significantly stimulate the migration of ovarian cancer cells." (PMID 39539540, 2024).
ovarian carcinoma (continued). "The expression of some immune-related molecules, such as IL-4, IL-6, IL-10, and GM-CSF, were analyzed, but none of them was found to be related to the induction of B7-H4 expression in ovarian cancer cells." (PMID 36609273, 2023). "EOC patients showed higher levels of proinflammatory cytokines (IL-6, TNF-α, and IL-12), regulatory cytokines (IL-10), and chemokines (CXCL-9 and CXCL-10), which corroborated this environmental proinflammatory/regulatory mechanism for the development of ovarian cancer." (PMID 38141599, 2023). "IL-10 transcripts are present in CD14+ leukocytes in the malignant ascites of ovarian cancer patients but not in the CD14− fraction and are only present in the HLA-DR− and not the HLA-DR+ CD14+ population." (PMID 34727230, 2022). "Other studies involving clinical material also corroborated our findings, by presenting a negative correlation between the survival time of ovarian cancer patients and the expression levels of IL-8 and IL-10." (PMID 35867729, 2022). "It has been revealed that IL-10 level was positively correlated with MDSCs expansion and tumor progression in patients with anaplastic thyroid cancer, ovarian cancer, gastric cancer and no-small cell lung cancer." (PMID 35004667, 2021). "Moreover, it has been shown that knockdown of STAT3 in macrophages that were co-cultured with SKOV3 human ovarian cancer cells inhibited cell proliferation of SKOV3 through the downregulation of IL-6 and IL-10 of macrophages." (PMID 32283687, 2020). "CD4+IL-17A+ TALs restimulated in ovarian cancer conditioned medium, but not in the presence of Th17-driving cytokines or TGFβ, demonstrate increased production of IL-10." (PMID 28290453, 2017). "The profile of these cytokines/receptors as well as simultaneous measurement of IL-10/CA-125 has not been investigated in Iranian patients with ovarian cancer and not compared to those with benign cysts." (PMID 25999622, 2015). "Accordingly, in an ovarian carcinoma-bearing mice model, IFN-γ-stimulated M-MDSC increased MHC class II, CD80, and IL-10 expression, and induced CD4+CD25+ Treg in a CTLA-4/CD80-dependent manner, which is in line with our results on IL-10-producing GM-CSF/IL-6 M-MDSC." (PMID 30936876, 2019). "Ovarian cancer cells can recruit and induce the expansion of regulatory T cells (Tregs), which are able to inhibit the anti-tumor response of effector CD8+ T cells, either by secretion of interleukin-10 (IL-10) and transforming growth factor-β (TGF-β) or via a cell-cell contact-dependent mechanism." (PMID 29342108, 2018). "Serum concentration of IL-10 in ovarian cancer patients correlated positively with peritoneal fluid concentration of this cytokine and serum level of TNF-alpha; moreover, women with ovarian malignancies showed a positive correlation between serum TNF-alpha an IL-10 in peritoneal fluid." (PMID 28376925, 2017). "Considering that it has already been demonstrated that PD-1 blockade induced IL-10 secretion by myeloid cells in ovarian cancer, these apparent discrepancies could be explained by the fact that six hours of in vitro treatment were not sufficient to allow IL-10 modulation by the anti-PD-1 antibody." (PMID 34439233, 2021). "HM-1 and ID8 mouse ovarian cancer cells expressed very low levels of VISTA, and the expression did not increase following treatment with IFN-γ, IL-4, IL-6, IL-10, IL-17, or TNF-α." (PMID 30382166, 2019). "Consistent with the hypothesis that the ovarian cancer microenvironment is influenced by inflammatory and immunosuppression molecules, we found higher concentrations of TGF-β, IL10 and IL8, but these soluble factors did not achieve satisfactory predictive values to discriminate ovarian malignancy." (PMID 36765633, 2023).
dengue (115 papers, 2007 to 2026). "In dengue virus infection, immune evasion was associated with increased expression of IL-10-mediated SOCS3, which subsequently inactivated JAK/STAT pathways." (PMID 37376550, 2023). "In fact, IL-10 emerged as a potential diagnostic marker for dengue fever, and CD121b (an IL-1 receptor) was demonstrated to be a predictive marker for severe dengue." (PMID 36423184, 2022). "Reduced numbers of Th1 cells have been reported in patients with severe dengue and are associated with the presence of Treg cells, production of IL-10, and downregulation of CD40L." (PMID 35372587, 2022). "Cytokines including TNF- α, IFN- γ, IL-1β, IL-2, IL-6 and IL-10 have been linked to the pathogenesis of other viral hemorrhagic diseases, such as dengue, and Ebola." (PMID 34793450, 2021). "We previously showed that serum IL-10 levels inversely correlated with T cell numbers in acute dengue and was associated with T cell apoptosis." (PMID 33199778, 2020). "In dengue patients who had cytokine measurement, acute serum IL-10 level was significantly associated with acute serum HA (r = 0.49, p = 0.012)." (PMID 28393899, 2017). "The biological role of IL-10 in dengue pathogenesis is not fully known; it has been associated with changes in vascular permeability, plasma leakage, thrombocytopenia, and altered levels of hepatic transaminases." (PMID 28827898, 2017). "There is another cytokine known as IL-10 that is implicated in the pathogenesis of severe dengue diseases." (PMID 26923481, 2016). "Our previous studies and others have shown that elevated IL-10 is associated with severe dengue, and therefore, we sought to investigate the changes in IL-10 levels throughout the clinical disease and its association with liver damage." (PMID 27391896, 2016). "Cytokine mediated liver damage has also been proposed as a mechanism, as high levels of IP-10 and IL-10 were found to associate with high liver transaminase levels in children with dengue." (PMID 27391896, 2016). "Since both IL-10 and IL-17 were significantly associated with SD, and high levels were seen very early in the illness, their role in the pathogenesis of dengue and dengue liver injury should be further investigated." (PMID 27391896, 2016). "We found that serum IL-10 levels indeed were significantly higher in patients with severe dengue and also significantly associated with other disease severity markers such as liver transaminase levels." (PMID 23883139, 2013). "Our data suggest that serum IL-10, TNFα and TGFβ differentially associate with dengue disease severity." (PMID 23209731, 2012). "As IL-10 was found to be associated with T cell apoptosis in patients with acute dengue, we proceeded to find out if IL-10 causes T cell apoptosis." (PMID 23209731, 2012). "Notably, previous studies showed that elevated IL-10 levels are associated with dengue pathogenesis and disease severity." (PMID 37235332, 2023). "We and others have found the association of IL-10 levels with dengue severity." (PMID 35372587, 2022). "IL-10 may cause lymphocyte dysfunction through the suppression of the T cell proliferative response to mitogens, which occurs in dengue patients during the early stages of infection." (PMID 33231723, 2021). "Since early appearance of IL-10 was the main cytokine that was associated with subsequent progression to severe dengue, IL-10 is likely to also contribute to disease pathogenesis by inhibiting virus specific T cell responses and therefore, a delay in virus clearance." (PMID 33194836, 2020). "Serum IL-10 was significantly associated with HA in all dengue patients (p = 0.002)." (PMID 28393899, 2017). "Further characterization of kinetics and cell source of IL-10 signaling at various stages of dengue disease may prove to be key to understanding the cause and effect of immune imbalance in SD." (PMID 26982706, 2016). "In addition, reduction in IL-8 and IL-10 was associated with improvement of clinical symptoms in severe dengue patients." (PMID 26982706, 2016).